GAS6 (growth arrest specific 6)
Description:
Ligand for tyrosine-protein kinase receptors AXL, TYRO3 and MER whose signaling is implicated in cell growth and survival, cell adhesion and cell migration. GAS6/AXL signaling plays a role in various processes such as endothelial cell survival during acidification by preventing apoptosis, optimal cytokine signaling during human natural killer cell development, hepatic regeneration, gonadotropin-releasing hormone neuron survival and migration, platelet activation, or regulation of thrombotic responses. (Microbial infection) Can bridge virus envelope phosphatidylserine to the TAM receptor tyrosine kinase Axl to mediate viral entry by apoptotic mimicry. Plays a role in Dengue cell entry by apoptotic mimicry. Plays a role in Vaccinia virus cell entry by apoptotic mimicry. Plays a role in ebolavirus and marburgvirus cell entry by apoptotic mimicry.
Synonyms: AXLLG; AXSF; FLJ34709; DKFZp666G247
Tractability: Antibody: UniProt places it where antibodies can reach, with high confidence; its Gene Ontology location is reachable by antibodies, with high confidence; UniProt predicts a signal peptide or a membrane-spanning region. PROTAC: its protein half-life has been measured. Other modalities: a drug acting on it is in phase 2 or 3 trials.
Target class: Secreted protein
Gene: Protein-coding gene on chromosome 13 (113,820,468 to 113,864,123, reverse strand). Ensembl gene ENSG00000183087.
Subcellular location: Secreted
Subcellular location (Human Protein Atlas): Cytosol; Centriolar satellite; Predicted to be secreted
Pathways (Reactome):
Metabolism of proteins: Gamma-carboxylation of protein precursors; Post-translational protein phosphorylation; Regulation of Insulin-like Growth Factor (IGF) transport and uptake by Insulin-like Growth Factor Binding Proteins (IGFBPs); Removal of aminoterminal propeptides from gamma-carboxylated proteins; Transport of gamma-carboxylated protein precursors from the endoplasmic reticulum to the Golgi apparatus
Hemostasis: Cell surface interactions at the vascular wall; Platelet degranulation
Disease: Dengue Virus Attachment and Entry
Gene Ontology:
Molecular function: cysteine-type endopeptidase inhibitor activity involved in apoptotic process; phosphatidylserine binding; protein binding; protein-macromolecule adaptor activity; receptor ligand activity; receptor tyrosine kinase binding; signaling receptor binding; calcium ion binding
Biological process: apoptotic cell clearance; B cell chemotaxis; calcium ion transmembrane transport; cell surface receptor signaling pathway; cellular response to interferon-alpha; cellular response to vitamin K; cellular response to xenobiotic stimulus; dendritic cell differentiation; fusion of virus membrane with host plasma membrane; hematopoietic stem cell migration to bone marrow; negative regulation of apoptotic process; negative regulation of biomineral tissue development; negative regulation of dendritic cell apoptotic process; negative regulation of DNA-templated transcription; negative regulation of endothelial cell apoptotic process; negative regulation of fibroblast apoptotic process; negative regulation of interleukin-1 production; negative regulation of interleukin-6 production; negative regulation of oligodendrocyte apoptotic process; negative regulation of tumor necrosis factor production; negative regulation of tumor necrosis factor-mediated signaling pathway; negative regulation of type II interferon production; phagocytosis; positive regulation of cytokine-mediated signaling pathway; positive regulation of dendritic cell chemotaxis; and 25 more
Cellular component: cytoplasm; extracellular exosome; extracellular region; endoplasmic reticulum lumen; endosome lumen; Golgi lumen; non-collagenous component of interstitial matrix; platelet alpha granule lumen
Genetic constraint (gnomAD): Loss-of-function variants: 42 observed, 69.04 expected, observed/expected ratio (o/e) 0.61, 90% interval 0.47 to 0.79. The upper end of that interval is the gene's LOEUF score, 0.79, which puts it in group 3 of 6, group 1 being the genes least tolerant of losing a copy. Missense variants: 854 observed, 887.48 expected, observed/expected ratio (o/e) 0.96, 90% interval 0.91 to 1.02. Synonymous variants: 432 observed, 384.38 expected, observed/expected ratio (o/e) 1.12, 90% interval 1.04 to 1.22.
Homologues: Orthologues: macaque GAS6 (86% identical), rat Gas6 (82% identical), pig GAS6 (81% identical), mouse Gas6 (81% identical), guinea pig GAS6 (79% identical), dog GAS6 (73% identical), tropical clawed frog gas6 (61% identical), zebrafish gas6 (49% identical). Paralogues in human: MEGF6 (23% identical), MEGF11 (19% identical), MEGF10 (18% identical).
Diseases named in the same sentence as GAS6 in open-access papers:
GAS6 is named in the same sentence as 253 diseases in open-access papers, as found by Europe PMC text mining. Sharing a sentence is not in itself a finding about the gene and the disease. The quoted sentences say what the papers report.
prostate carcinoma (47 papers, 2008 to 2025). A carcinoma that arises from epithelial cells of the prostate gland. "Here we show that dormancy-associated signals in prostate cancer, Gas6 and TGFß2, rapidly within a few hours, induce quiescence entry in prostate cancer cells after mitosis." (PMID 34957090, 2021). "AXL phosphorylation and activation by binding of GAS6 has been associated with increased cell proliferation and survival in various tissues and cancer types including prostate cancer, colorectal cancer, gastric cancer, renal carcinoma and osteosarcoma." (PMID 31694201, 2019). "Gas6 binds to receptor tyrosine kinases: Tyro3, MerTK, and Axl, of which the expression of the latter in prostate cancer cells is associated with increased tumor grade and bone metastasis but not lymph node metastasis." (PMID 29642534, 2018). "For example, AXL is an important receptor tyrosine kinase that is expressed by prostate cancer DTCs and responds to growth arrest-specific 6 (Gas6) protein secreted by osteoblasts and promotes dormancy by limiting DTC proliferation." (PMID 39796673, 2024). "Gas6 promotes the proliferation of AXL-expressing prostate cancer cells by enhancing Akt phosphorylation." (PMID 37265798, 2023). "Ack1 was identified as a major tyrosine-phosphorylated protein in LNCaP prostate cancer cells that were stimulated with Gas6 to activate Mer." (PMID 37662484, 2023). "GAS6 has been shown to down-regulate AXL in prostate cancer cells, GAS6 production by aHSCs has previously been described in the context of fibrosis, and its deficiency reduced fibrosis in mice." (PMID 37004869, 2023). "Within the bone marrow, elevated TGF-β and BMP pathway activation can maintain dormancy in head and neck squamous cell and prostate cancers through growth arrest-specific 6 (GAS6) and its receptor Axl." (PMID 37440925, 2023). "In preclinical models of prostate cancer, tumor cell homing was significantly higher in the hind limb than the fore limb bones, which was negatively correlated with levels of secreted GAS6 in these bones." (PMID 38203403, 2023). "By regulating GAS6 signaling in osteoblasts, NE induces dormant prostate cancer cells to proliferate and promotes the occurrence and development of prostate cancer." (PMID 34988010, 2021). "For example, decreased TGF-β and GAS6 expression by osteoblasts can release dormant prostate cancer cells from dormancy." (PMID 34831167, 2021). "For example, ligand growth arrest-specific 6 protein (GAS6)/AXL interaction with osteoblasts retains bone-metastatic prostate cancer cells in a dormant state." (PMID 34831167, 2021). "Gas6/Axl can promote bone marrow and lung cancer metastasis and invasion as well as prostate cancer cell survival." (PMID 32432570, 2020). "Accordingly in a prostate cancer model, osteoblasts induce mTOR signaling by releasing GAS6, and this preserves CSC dormancy." (PMID 33193295, 2020). "The critical role of GAS6-AXL signaling in prostate cancer cell invasion was previously reported using shRNA targeting AXL in Boyden chamber assays under serum-free conditions with GAS6 as a chemoattractant." (PMID 32055714, 2020). "TGF-β2 was found to induce dormancy of disseminated prostate cancer cells through upregulation of p27 and growth arrest-specific 6 (GAS6), and then re-enter the cell cycle." (PMID 31753020, 2019). "In prostate cancer, it has been demonstrated that GAS6/AXL and transforming growth factor-beta 2 (TGF-β2) signaling regulates tumor cell dormancy." (PMID 31694201, 2019). "Gas6/AxL can induce invasion and survival during prostate cancer cell bone marrow metastasis, and also promotes invasion and metastasis of gastric cancer and lung cancer." (PMID 31110076, 2019). "The results of animal experiments have shown that human prostate cancer cell lines grow significantly better in transplanted vertebral bodies derived from Gas6−/− animals than in those derived from Gas6+/+ animals." (PMID 29386018, 2018).
prostate carcinoma (continued). "Together, this suggests that Gas6-Axl interactions at the endosteal niche can induce both quiescence and treatment resistance, and therefore dormancy, in prostate cancer." (PMID 29642534, 2018). "Another study also indicated that the Gas6/Axl axis induces the invasion of prostate cancer cells to the bone marrow and enhances cell survival during metastasis." (PMID 29386018, 2018). "GAS6 in turn binds to the receptor Axl and results in the suppression of prostate cancer cell growth." (PMID 29874869, 2018). "Consistently when prostate cancer cells reach the bone marrow Axl expression in prostate cells and GAS6 expression in osteoblasts both increase simultaneously." (PMID 30180883, 2018). "For instance, Gas6 promotes proliferation of prostate carcinoma cell lines expressing Axl by inducing phosphorylation of Akt and MAPK." (PMID 29386018, 2018). "Prostate cancer cells also exhibited decreased growth in a bone environment from Gas6+/+ animals in comparison to Gas6−/− animals." (PMID 29642534, 2018). "Through self-regulatory mechanisms, the binding of Gas6 to Axl results in the downregulation of Axl in prostate cancer cells in vitro." (PMID 29642534, 2018). "There is also evidence that GAS6 increases the number of prostate cancer cells with a stem cell phenotype, which is CD133 positive/CD44 positive, within the bone marrow." (PMID 30180883, 2018). "We previously identified that the osteoblastic niche regulates the proliferation of prostate cancer via the GAS6 pathway." (PMID 27172799, 2016). "We found that GAS6 triggered mTOR signaling in prostate cancer, with increases seen in both mTORC1 and mTORC2, and these were diminished by the mTORC1 inhibitor rapamycin and the dual mTORC1/2 inhibitor pp242." (PMID 27172799, 2016). "Previously we have demonstrated that GAS6 signaling regulates invasion, proliferation, chemotherapy-induced apoptosis of prostate cancer (PCa) cells." (PMID 27028863, 2016). "That is, human prostate cancer xenografts grow rapidly in the osseous environment expressing less GAS6, compared to high GAS6-expressing bones." (PMID 27172799, 2016). "With further analysis, we found that within the marrow the osteoblastic niche controls conversion of disseminated prostate cancer cells to CSCs through the GAS6/Mer/mTOR pathway." (PMID 27172799, 2016). "When prostate cancer cells were co-cultured with osteoblasts isolated from GAS6-null mice, the conversion to CSCs was significantly, although not completely, diminished." (PMID 27172799, 2016). "Consistently, when prostate cancer reaches the bone, Axl expression in prostate cancer and GAS6 expression in osteoblasts both increase simultaneously." (PMID 27172799, 2016). "Here we investigated the role that endogenous GAS6 and Mer receptor signaling plays in establishing prostate cancer stem cells in the bone marrow microenvironment." (PMID 27028863, 2016). "Regardless, it will be important to determine the regulation of Axl and Gas6 in these contexts in order to fully understand the contribution of Axl signaling to the progression of prostate cancer." (PMID 25344858, 2014). "Recent work has shown that prostate cancer (PCa) cell lines express the growth-arrest specific 6 (GAS6) receptors Axl, Tyro3, and Mer, and become growth arrested in response to GAS6." (PMID 23637920, 2013). "GAS6 was also shown to dose dependently inhibit the proliferation of the prostate cancer cell lines PC3 and DU145, but the opposite effect was reported on the same cell lines by another group." (PMID 23878800, 2013). "Additionally, growth arrest specific-6 (GAS6), a ligand secreted by osteoblasts in the bone marrow environment, contributes to the dormancy of prostate cancer-derived DTCs and inhibits the proliferation of hematopoietic progenitors." (PMID 37259089, 2023). "Indeed, once prostate cancer cells reach the osteoblastic niche, secretion of GAS6 by osteoblasts is upregulated, inducing growth arrest in cancer cells." (PMID 38203403, 2023).
prostate carcinoma (continued). "Binding of gas6 to TAM receptors is associated with the carcinogenetic mechanisms of multiple malignancies, such as in breast cancer, chronic lymphocytic leukemia, non-small cell lung cancer, melanoma, prostate cancer, etc., and shortened overall survival." (PMID 37265798, 2023). "Given that RON signaling in prostate cancer cells promotes CCL2 production, which recruits tumor-associated macrophages, the secretion of GAS6 by tumor-associated macrophages to then promote RON activation adds an additional layer of cellular crosstalk to sustain RON signaling within the TME." (PMID 36833444, 2023). "GAS6 can promote prostate cancer survival by cell cycle arrest and apoptosis inhibition." (PMID 35075375, 2022). "Notably, several studies using different prostate cancer dormancy models have also shown Cfh and Gas6, two of our top dormancy-related genes, are consistently up-regulated in dormant cancer cell populations." (PMID 35093137, 2022). "GAS6 was one of the genes in an early-stage prostate cancer diagnosis model." (PMID 35075375, 2022). "In the bone marrow, Gas6 and TGFß2 are thought to promote prostate cancer dormancy while GM-CSF promotes stem cell release from the bone marrow, which may provide cues for metastatic cancer cells in the bone marrow to exit from dormancy and proliferate." (PMID 34957090, 2021). "Strengthening these findings, more recently, the activation of mTOR was able to enrich the pool of CSCs within DCCs in bone marrow (BM) metastatic niches in prostate cancer models, through a mechanism involving the release of growth arrest specific 6 (GAS6) by osteoblasts." (PMID 33193295, 2020). "Furthermore, one study showed that Gas6 is amplified in breast cancer, and human prostate cancer cell lines were found to grow significantly better in vertebral bodies transplanted from Gas6-/- animals than in those derived from Gas6 +/+ animals." (PMID 32899501, 2020). "Recent studies have shown that the Gas6/Axl complex promotes bone marrow metastasis of prostate cancer cells by inducing invasion and survival, and studies have also shown that Gas6/Axl was closely related to the invasion and metastasis of gastric cancer and non-small-cell lung cancer." (PMID 31110076, 2019). "GAS6 was important for the migration and invasion of prostate cancer cells." (PMID 30970615, 2019). "Moreover, human prostate cancer cell lines were found to grow significantly better in vertebral bodies transplanted derived from Gas6−/− animals than in those derived from Gas6+/+ animals." (PMID 29386018, 2018). "The hypoxic bone marrow may therefore stabilize Gas6-Axl interactions between osteoblasts and prostate cancer cells, maintaining long-term adhesion to the niche and dormancy." (PMID 29642534, 2018). "Mechanisms specific to cancer dormancy in the bone endosteal niche have been described in the context of prostate cancer, for which the binding of annexin II receptor expressing prostate cancer cells to osteoblasts promotes the expression and secretion of growth arrest-specific 6 (GAS6)." (PMID 29874869, 2018). "Activation of AXL often occurs upon binding to Gas6, including in prostate cancer." (PMID 28455956, 2017). "However, in the present study we discovered a new, important role for GAS6 in the progression of prostate cancer in the marrow: GAS6 expressed by osteoblasts converts disseminated prostate cancer to a stem-like phenotype through its receptor, Mer." (PMID 27172799, 2016). "The growth of prostate cancer in the marrow depends on the levels of GAS6 that bones express." (PMID 27172799, 2016). "Notably, hypoxia has been found to prevent GAS6-mediated down-regulation of Axl in prostate cancer cells." (PMID 26760782, 2016). "In addition, GAS6 produced by osteoblasts prevents prostate cancer cell proliferation and protects prostate cancer cells from chemotherapy-induced apoptosis." (PMID 27782035, 2016).